TNF (tumor necrosis factor)
Diseases named in the same sentence as TNF in open-access papers (continued):
Sharing a sentence is not in itself a finding about the gene and the disease.
CNS demyelination (3 papers, 2013 to 2025). A loss of myelin from nerve fibers in the central nervous system. "In this paper, we review the published case reports of CNS demyelination associated with anti-TNF-α therapy and present the follow-up of our 4 previously reported patients who developed neurologic symptoms suggestive of CNS demyelination after having received anti-TNF-α treatment." (PMID 28337644, 2017). "A systematic review by Sicotte and Voskuhl identified over 120 cases of CNS demyelination in patients receiving anti-TNF agents." (PMID 41450349, 2025). "We conducted a PubMed literature search of available material on documented CNS demyelination in patients receiving TNF-α blockers." (PMID 28337644, 2017).
cognitive (3 papers, 2014 to 2023). "Inhibition of TNF-α can reduce cognitive deficits induced by Aβ." (PMID 34106880, 2021).
congenital ichthyosis (3 papers, 2020 to 2022). "g., anti-TNF-α, anti-IL-17, and anti-IL-4/IL-13 antibodies) have been reported as useful treatments for several types of inherited ichthyoses." (PMID 36332686, 2022). "Recently, significant upregulation of IL-17/tumor necrosis factor alpha (TNF-α)-related genes has been reported in autosomal recessive congenital ichthyosis patients." (PMID 32425927, 2020). "In different types of ichthyosis, high levels of IL-17 and TNF-α were documented." (PMID 34082764, 2021). "Furthermore, clinically, anti-inflammatory therapies (e.g., anti-TNF-α antibodies, anti-IL-17 antibodies) have been reported as useful treatments for inherited ichthyoses and in other AiKDs." (PMID 32425927, 2020).
crescentic glomerulonephritis (3 papers, 2020 to 2024). A histopathologic term for a pattern of diseases characterized by extensive crescent formation in the glomeruli; patients present clinically with rapid deterioration of renal function, and possible progression to end-stage renal failure within weeks or months. "In an experimental study of crescentic glomerulonephritis, the administration of anti-TNF-α monoclonal antibody reduced glomerular inflammation, crescent formation, and tubulointerstitial scarring with preservation of renal function." (PMID 38004064, 2023). "Anti-TNF-α blocker has been proved to reduce glomerular inflammation, tubulointerstitial scarring, and restore renal function in experimental crescentic glomerulonephritis." (PMID 32765640, 2020).
dermatophytosis (3 papers, 2017 to 2023). A common fungal infection of the stratum corneum of the skin, hair, or nails by a dermatophyte. "Our biosynthesized AS-AgNPs recapitulate the effect of nitric oxide-releasing AgNPs, which have been recently shown to down-regulate the production of IL-2, 6, 10 and TNFα, upon topical application in a mouse model of T. rubrum dermatophytosis." (PMID 36838531, 2023). "Defects in these receptors severely impair the production of interferon γ (IFN-γ), tumor necrosis factor α (TNF-α), interleukin-1β (IL-1β), IL-10, and IL-6, culminating in deep dermatophytosis." (PMID 38022599, 2023).
diabetic ketoacidosis (3 papers, 2016 to 2025). The metabolic condition resulted from uncontrolled diabetes mellitus, in which the shift of acid-base status of the body toward the acid side because of loss of base or retention of acids other than carbonic acid is accompanied by the accumulation of ketone bodies in body tissues and fluids. "The pro-inflammatory cytokines (IL-6 and TNF-alpha) in diabetic ketoacidosis regulate the expression of vascular endothelial growth factor, ultimately increasing vascular permeability, which then causes the vasogenic cerebral edematous changes seen in PRES." (PMID 34840779, 2021).
Ductal Carcinoma (3 papers, 2011 to 2022). "Individuals with ductal carcinoma recorded significant differences (p<0.001) in the mean levels of the interleukin-19 and TNF-α compared with healthy groups." (PMID 35928364, 2022). "Gong demonstrated that increased TNF-α promotes invasion and metastasis in ductal carcinomas in a scalar fashion." (PMID 21345194, 2011). "Additionally, BCP with ductal carcinoma showed significant differences in the mean levels of IL-19 and TNF-α in comparison with healthy people." (PMID 35928364, 2022).
Ebola (3 papers, 2011 to 2025). "Some of the genes that had already been implicated in the pathogenesis of Ebola hemorrhagic fever such as IL-6 and TNF-α were induced after 1 h, but returned towards basal levels of expression after 6 h." (PMID 22028943, 2011). "In addition, one study which compared survivors with PES to survivors without sequelae found had an increased CD8+ T-cell and CD4+ T-cell expression of IFNγ and TNFα following stimulation with Ebola antigens." (PMID 40561148, 2025).
Enterovirus infection (3 papers, 2015 to 2025). "Subsequently, the enterovirus infection induced a surge of pro-inflammatory cytokines, resulting in elevated levels of pro-inflammatory and inflammatory cytokines, including TNF-α." (PMID 39956903, 2025). "Enteroviral infection can induce cytokine storm in a variety of tissues, which is characterized by marked upregulation of key inflammatory mediators, including cytokines (e.g., IL-6, TNF-α), chemokines (e.g., MCP-1), and COX-2, etc.." (PMID 41300404, 2025).
Erythema nodosum (3 papers, 2014 to 2023). An erythematous eruption commonly associated with drug reactions or infection and characterized by inflammatory nodules that are usually tender, multiple, and bilateral. "On studying the immune pattern in cases of leprosy infection, Foss found an increase in TNF-α production associated with high levels of C-reactive protein, suggesting that TNF-α was involved in the inflammatory reaction of erythema nodosum." (PMID 26339136, 2015).
Failure to thrive (3 papers, 2011 to 2023). Failure to thrive (FTT) refers to a child whose physical growth is substantially below the norm. "The young age, together with severe diarrhea and failure to thrive, and the low response rate to anti-TNFα medications, are possible causes of the high rates of TPN initiation in IO-IBD." (PMID 36937967, 2023). "However, at higher doses neonates had a slowing of growth (or failure to thrive) after day 9 and this did not correlate with TNF-α expression." (PMID 22185352, 2011).
follicular disorders (3 papers, 2022 to 2026). "Moreover, the key proinflammatory TNF-α signaling pathway was prominently downregulated in DPCs after ADSC-Exos treatment, suggesting that ADSC-Exos might play an anti-inflammatory role in hair disorders." (PMID 35155688, 2022).
Gastrointestinal inflammation (3 papers, 2022 to 2025). Inflammation of the alimentary part of the gastrointestinal system. "Studies have revealed that the main characteristics of CAP-induced GI inflammation in mice are elevated levels of inflammatory cytokines, especially IL-10, IL-1β, and TNF-α." (PMID 35267319, 2022). "Similarly, increased amounts of various inflammatory mediators (e.g., interleukin [IL]-1β, IL-6, interferon gamma [IFN-γ], and tumor necrosis factor alpha [TNF-α]) in the stool samples of patients with PD indicate the presence of gastrointestinal inflammation." (PMID 38098067, 2023).
geographic atrophy (3 papers, 2021 to 2025). "Tumor necrosis factor alpha (TNF-α) is an inflammatory cytokine implicated in pathological changes to the retinal pigment epithelium that are similar to changes in geographic atrophy (GA), an advanced form of age related macular degeneration (AMD)." (PMID 38984140, 2024). "For example, TNF-α induces retinal ischaemia–reperfusion injury and axonal degeneration, and chronic elevation can lead to retinal pigment epithelium cell death and morphological changes resembling geographic atrophy, which is a late stage of AMD." (PMID 41465162, 2025). "To this end, we measured ex vivo mRNA expression of the cytokines TNF-α, IL-6, and IL-10 in whole blood samples after stimulation with A2E in a clinical sample of 27 patients with neovascular AMD and 24 patients with geographic atrophy secondary to AMD." (PMID 33859228, 2021). "After stimulation with A2E, no statistical differences were found in the median expression level of TNF-α, IL-6, IL-10 between the control group, and the neovascular AMD and the geographic atrophy group." (PMID 33859228, 2021).
heart injury (3 papers, 2012 to 2025). Injury to the heart. "Previous study indicated that TNF-alpha expression was reduced by cinnamic acid and cinnamic aldehyde in ISO-induced heart injury rats." (PMID 27936072, 2016).
hemangioma (3 papers, 2013 to 2025). A benign vascular lesion characterized by the formation of capillary-sized or cavernous vascular channels. "IL-23 inhibitors were linked to increased angioma formation compared to TNF-α inhibitors, while methotrexate and UVB therapy appeared to have a protective effect." (PMID 40282856, 2025). "Our results indicate that biologically naïve patients and those receiving TNF-α inhibitors had lower angioma counts compared to those treated with IL-23 inhibitors (5.89 ± 5.53 and 5.06 ± 4.39 vs. 6.94 ± 7.00)." (PMID 40282856, 2025). "Patients not receiving biologic therapy (biologic-naïve: 5.89 ± 5.55) and those treated with TNF-α inhibitors (5.06 ± 4.39) had lower angioma counts than those on IL-23 inhibitors (6.94 ± 7.00)." (PMID 40282856, 2025). "Additionally, patients receiving IL-23 inhibitors exhibited greater angioma counts compared to those on TNF-α inhibitors, indicating a potential pro-angiogenic effect of IL-23 blockade, possibly mediated through VEGF modulation." (PMID 40282856, 2025).
hemolytic-uremic syndrome (3 papers, 2012 to 2022). Acute kidney injury associated with microangiopathic hemolytic anemia and thrombocytopenia. "Monocyte and macrophage cells are the cellular components of innate immunity that have the major role in the pathogenesis of hemolytic uremic syndrome via production of proinflammatory cytokines including soluble cytokines TNF- α and IL-1β." (PMID 25035861, 2014).
hemophilia B (3 papers, 2019 to 2020). Hemophilia B is a form of hemophilia characterized by spontaneous or prolonged hemorrhages due to factor IX deficiency. "First, we determined the efficacy of TNFα inhibition as an adjunctive therapy in the protection against joint damage after recurrent intra-articular hemorrhage in a hemophilia B mouse model." (PMID 31892201, 2019). "INS regulates vascularization; APOH, F2, and ICAM regulate platelet activation and adhesion; AGT regulates blood vessel contraction; TNF and CCL2 regulate blood chemokine in circulation; F9 regulates onset Hemophilia B, and PON1 inhibits onset cardiovascular disease." (PMID 32753925, 2020).
Hepatomegaly (3 papers, 2010 to 2020). Abnormally increased size of the liver. "Accordingly, we demonstrated that the F3 peptide vaccine was capable of increasing the IDR and the ratios of TNF-α/IL-10 CD4+ T cells and of decreasing the parasite load and hepatomegaly." (PMID 21085470, 2010).
hepatopulmonary syndrome (3 papers, 2007 to 2021). Hepatopulmonary syndrome (HPS) is a lung disease characterized by widening of arteries and veins (dilatation) in the lungs in people who have chronic liver disease. "However, exogenous administration of endothelin-1 to partial portal vein ligated rats increased TNF-α levels, increased pulmonary cNOS production and pulmonary intravascular macrophage accumulation, and led to the development of hepatopulmonary syndrome." (PMID 17999758, 2007).
hereditary thrombophilia (3 papers, 2023 to 2025). "According to these outcomes, patients with hereditary thrombophilia may experience recurrent pregnancy losses with elevated levels of IL-6 and TNF-α." (PMID 38533322, 2024).
herpes simplex encephalitis (3 papers, 2020 to 2024). Herpes simplex virus encephalitis (HSE) is caused by the infection of the central nervous system by Herpes simplex virus (HSV) that could have a devastating clinical course and a potentially fatal outcome particularly with delay or lack of treatment. "During the ascending phase of herpes simplex encephalitis, the expression of CTRP4 in the brain was closely related to serum levels of IL‐6 and TNF‐α, volumes of brain damage, and the decline in MMSE scores." (PMID 38334009, 2024).
Hirsutism (3 papers, 2015 to 2025). Abnormally increased hair growth referring to a male pattern of body hair (androgenic hair). "It has also been demonstrated that melatonin supplementation, particularly when combined with magnesium, has beneficial effects in patients with PCOS, improving parameters such as hirsutism, BMI, waist circumference, and serum levels of TNF-alpha." (PMID 41041518, 2025). "Oner and muderris showed ω-3 also may be effective in decreasing hirsutism, BMI, LH, testosterone, insulin, Homeostatic model assessment (HOMA) levels, and increasing Sex hormone-binding globulin (SHBG) and TNF-α in women with PCOS." (PMID 25653669, 2015).
Histiocytosis (3 papers, 2021 to 2024). An excessive number of histiocytes (tissue macrophages). "Dogs with L. infantum infection in the bone marrow presented with histiocytosis (p = 0.0046), fewer erythroid cell clusters (p = 0.0127) and increased gene expression levels of IFN-γ (p = 0.0015) and TNF (p = 0.0091)." (PMID 34442696, 2021).
HTLV infection (3 papers, 2017 to 2022). "As HAM/TSP is an insidious complication of HTLV infection, long-term cohort studies are necessary to definitively validate the link between TNF and MMP-9 production in the context of HAM/TSP development." (PMID 36311773, 2022). "A correlation between proinflammatory and anti-inflammatory cytokines has been observed in subjects with HTLV infection, and there is a direct correlation between IFN-γ and IL-10 as well in TNF and IL-10 in HTLV-1 carriers." (PMID 32385802, 2020). "Although TNF possesses antiviral properties, in the context of HTLV infection, its production does not seem to contribute to viral killing, as TNF has been observed to positively correlate with proviral load." (PMID 36311773, 2022).
hypertensive nephropathy (3 papers, 2016 to 2025). Kidney damage that results from chronically elevated blood pressure; complications include glomerular damage resulting in proteinuria and hematuria. "Cytokines IL-1β, IL-6, and TNF-α play a significant role in the occurrence and development of hypertensive nephropathy." (PMID 27069492, 2016). "In elderly individuals with hypertensive nephropathy, elevated levels of NGAL, KIM-1, IL-18, TNF-α, IL-6, NF-κB, and FMO3 were observed, accompanied by reduced urinary TMAO concentrations and impaired renal function, as indicated by increased serum creatinine and decreased eGFR." (PMID 40978750, 2025).
hypogonadotropic hypogonadism (3 papers, 2013 to 2024). Abnormal ovarian or testicular function due to insufficient hormonal stimulation from the hypothalamic-pituitary axis. "In T2D, secondary hypogonadism may result from both peripheral and central IR, aggravated by pro-inflammatory cytokines like Tumor Necrosis Factor Alpha (TNF-α) and Interleukin 6 (IL-6) that influence the HPG axis." (PMID 38892561, 2024).
hypopharyngeal carcinoma (3 papers, 2021 to 2024). Carcinoma, predominantly squamous cell, arising from the epithelial cells of the hypopharynx. "We also show that all three STAT3 inhibitors, with STA‐21 having the most profound effect, can effectively suppress the continuous production of cancer‐related molecules, IL6, TNF, RELA(p65), EGFR, BCL2 and STAT3, previously associated with hypopharyngeal cancer, caused by acidic bile." (PMID 34850540, 2022). "KEGG results showed that Radix Astragali acted on hypopharyngeal carcinoma through multiple signaling pathways, such as PI3K-Akt signaling pathway, IL-17 signaling pathway, TNF signaling pathway, and PD-L1 expression and PD-1 checkpoint pathway in cancer." (PMID 38177197, 2024).
Hypotension (3 papers, 2021 to 2025). "Hypotension and cardiovascular instability are the most common side effects of hemodialysis and have been connected with IL-1 and TNF-a synthesis in monocytes." (PMID 33459124, 2021). "Furthermore, TNF-α can harm blood vessel linings, reducing the production of nitric oxide, which decreases vascular elasticity and can lead to autonomic nervous system dysfunction and orthostatic hypotension." (PMID 41157172, 2025).
idiopathic pneumonia syndrome (3 papers, 2014 to 2021). "In humans, as an anti-TNF antibody, etanercept is used to treat noninfectious idiopathic pneumonia syndrome which similar to virus-related pneumonia in some ways." (PMID 34725309, 2021).
infective endocarditis (3 papers, 2012 to 2025). Infective endocarditis (IE) is an infection of the inner lining of the heart chambers (endocardium) and valves. "We report the case of a man with infective endocarditis due to the TNF-α inhibitor, infliximab, for the management of psoriatic erythroderma." (PMID 28179019, 2017). "Our results are consistent with previous studies showing that TNF-α is produced by human monocytes stimulated with RGP and that a serotype c S. mutans mutation that reduces the glucose content in the RGP is less likely to induce infective endocarditis in rats." (PMID 39976456, 2025).
inflammatory demyelinating neuropathy (3 papers, 2019 to 2025). "AIDP- “Acute Inflammatory Demyelinating Polyneuropathy,” AMAN- “Acute Motor Axonal Neuropathy,” AMSAN- “Acute Motor and Sensory Axonal Neuropathy,” MFS- “Miller Fisher Syndrome,” TNF- “Tumor Necrosis Factor,” IL- “Interleukin”." (PMID 38600592, 2024). "CXCL13 appears to be more specific for representing inflammatory demyelinating neuropathy compared with the previously demonstrated cytokines such as HGF, TNF-α and CCLs for several reasons." (PMID 31712675, 2019).
Inguinal hernia (3 papers, 2016 to 2024). Protrusion of the contents of the abdominal cavity through the inguinal canal. "Besides, both TFRC and TNF could significantly increase the risk of inguinal hernia (TFRC: IVW: OR [95%]=1.0028 [1.0009 to 1.0046], p = 0.003; TNF: Wald ratio: OR [95%]=1.0009 [1.0 to 1.0019], p = 0.04)." (PMID 38591204, 2024). "IL-6 and TNF-α were separately studied in different groups and in a smaller cohort of patients, comparing traditional surgery with prosthetic repair for inguinal hernia." (PMID 27310955, 2016). "The oxidative stress is strongly related to the quantity of polypropylene for inguinal hernia repair, and is prodromal to TNF-α increase." (PMID 27310955, 2016).
Interstitial pneumonitis (3 papers, 2014 to 2019). "In addition, membrane-bound proteinases, such as proteinase 3 that is involved in activation and inactivation modes of PAR-2, was also expressed in neutrophils and alveolar macrophages clearing TNF-α, which is more common in interstitial pneumonitis than in SARC." (PMID 25009615, 2014). "Smoking may influence TNF-mediated systemic inflammation, such as in COPD or interstitial pneumonitis." (PMID 31426531, 2019).
intestinal polyp (3 papers, 2012 to 2023). Discrete abnormal tissue masses that protrude into the lumen of the intestine. "The administration of a 2% curcumin diet decreased the total number of intestinal polyps by 75% and reduced IL-1β, IL-6 and TNF-α protein expression." (PMID 36547085, 2022). "We then examined the inhibitory effect of Riccardin D on the expressions of TNF-α, COX-2 and PGE2 in intestinal polyps." (PMID 22432006, 2012). "The inhibitory effect of Riccardin D on TNF-α and COX-2 expression was further evidenced by RT-PCR analysis of small intestinal polyps." (PMID 22432006, 2012). "Moreover, when immunological parameters were evaluated in volunteers diagnosed with intestinal polyps and examined as a function of the presence or absence of ACF, TNF-α showed a statistically significant increase in subjects with ACF." (PMID 38003638, 2023).
iritis (3 papers, 2016 to 2024). Inflammation of the iris. "However, UG cases with cells in the anterior chamber (n = 11), suggesting the existence of active iritis, showed higher levels of IL-8 (P = 0.0002), TNF-α (P = 0.0037), and PDGF-AB/BB (P = 0.0009)." (PMID 26771310, 2016).